WEE2-AS1 (WEE2 antisense RNA 1)
Gene: Long non-coding RNA gene on chromosome 7 (141,704,003 to 141,738,346, reverse strand). Ensembl gene ENSG00000228775.
Gene Ontology:
Molecular function: pre-mRNA 5'-splice site binding
Biological process: mRNA 5'-splice site recognition
Cellular component: U1 snRNP